IL33 (interleukin 33)
Description:
Cytokine that binds to and signals through the IL1RL1/ST2 receptor which in turn activates NF-kappa-B and MAPK signaling pathways in target cells. Involved in the maturation of Th2 cells inducing the secretion of T-helper type 2-associated cytokines. Also involved in activation of mast cells, basophils, eosinophils and natural killer cells. Acts as an enhancer of polarization of alternatively activated macrophages. Acts as a chemoattractant for Th2 cells, and may function as an 'alarmin', that amplifies immune responses during tissue injury. Induces rapid UCP2-dependent mitochondrial rewiring that attenuates the generation of reactive oxygen species and preserves the integrity of Krebs cycle required for persistent production of itaconate and subsequent GATA3-dependent differentiation of inflammation-resolving alternatively activated macrophages (By similarity). In quiescent endothelia the uncleaved form is constitutively and abundantly expressed, and acts as a chromatin-associated nuclear factor with transcriptional repressor properties, it may sequester nuclear NF-kappaB/RELA, lowering expression of its targets. This form is rapidely lost upon angiogenic or pro-inflammatory activation.
Synonyms: NF-HEV; C9orf26; IL1F11; DVS27; DKFZp586H0523; NFEHEV
Tractability: Antibody: a drug acting on it is in phase 2 or 3 trials; UniProt places it where antibodies can reach, with high confidence; its Gene Ontology location is reachable by antibodies, with high confidence.
Target class: Secreted protein
Gene: Protein-coding gene on chromosome 9 (6,215,136 to 6,257,983, forward strand). Ensembl gene ENSG00000137033.
Subcellular location: Nucleus; Chromosome; Cytoplasm; Cytoplasmic vesicle, secretory vesicle; Secreted
Subcellular location (Human Protein Atlas): Nucleoplasm; Vesicles; Predicted to be secreted
Pathways (Reactome):
Signal Transduction: PI5P, PP2A and IER3 Regulate PI3K/AKT Signaling; PIP3 activates AKT signaling
Immune System: Interleukin-33 signaling
Metabolism of proteins: Ub-specific processing proteases
Gene Ontology:
Molecular function: cytokine activity; protein binding; interleukin-33 receptor binding
Biological process: negative regulation of inflammatory response to wounding; negative regulation of transcription by RNA polymerase II; positive regulation of chemokine production; positive regulation of macrophage activation; antibacterial innate immune response; inflammatory response; interleukin-33-mediated signaling pathway; macrophage differentiation; negative regulation of macrophage proliferation; positive regulation of cellular defense response; positive regulation of cytokine production; positive regulation of gene expression; positive regulation of glycoprotein biosynthetic process; positive regulation of inflammatory response; positive regulation of interleukin-6 production; positive regulation of neuroinflammatory response; positive regulation of transcription by RNA polymerase II; positive regulation of tumor necrosis factor production; gene expression; macrophage activation involved in immune response; microglial cell activation involved in immune response; microglial cell proliferation; negative regulation of immunoglobulin production; negative regulation of leukocyte migration; negative regulation of T-helper 1 type immune response; and 7 more
Cellular component: chromosome; cytoplasm; extracellular region; nucleoplasm; nucleus; decoy receptor complex; receptor complex; transport vesicle
Genetic constraint (gnomAD): Loss-of-function variants: 17 observed, 14.93 expected, observed/expected ratio (o/e) 1.14, 90% interval 0.78 to 1.68. The upper end of that interval is the gene's LOEUF score, 1.68, which puts it in group 6 of 6, group 1 being the genes least tolerant of losing a copy. Missense variants: 220 observed, 196.58 expected, observed/expected ratio (o/e) 1.12, 90% interval 1 to 1.25. Synonymous variants: 77 observed, 64.53 expected, observed/expected ratio (o/e) 1.19, 90% interval 0.99 to 1.44.
Homologues: Orthologues: chimpanzee IL33 (100% identical), macaque IL33 (94% identical), pig IL33 (64% identical), dog IL33 (60% identical), guinea pig IL33 (57% identical), rat Il33 (52% identical), mouse Il33 (51% identical).
Diseases named in the same sentence as IL33 in open-access papers:
IL33 is named in the same sentence as 691 diseases in open-access papers, as found by Europe PMC text mining. Sharing a sentence is not in itself a finding about the gene and the disease. The quoted sentences say what the papers report.
asthma (739 papers, 2008 to 2026). "Together, these data reveal the importance of the asthma-associated human 5 kb region in regulating human IL33 expression in a cell type- and context-dependent manner." (PMID 42100869, 2026). "Compared with wild-type mice, IL-33-deficient mice presented attenuated eosinophilic pulmonary inflammation in an OVA-induced asthma model." (PMID 39962262, 2025). "Polymorphisms in genes for alarmins (TSLP and IL‐33) and type 2 cytokines (IL‐4 and IL‐13) influence asthma risk and severity, although many genetic contributors remain unidentified." (PMID 40679787, 2025). "Cytokines produced by RV infection, including IL-5, IL-13, IL-25, and IL-33, have been linked to severe and long-lasting asthma." (PMID 40746413, 2025). "The epithelial expression of IL-33 is upregulated in asthma and COPD and is associated with disease severity." (PMID 41048933, 2025). "Support for IL-33 as a central mediator of human airway disease is derived from genome-wide association studies, and analysis of specimens from human asthma and patients with chronic obstructive pulmonary disease (COPD)." (PMID 40553562, 2025). "Overall, IL-33, as well as its receptors and complexes, has the potential to become a biomarker associated with asthma development and also treatment response." (PMID 40723867, 2025). "Although elevated serum levels inhibit IL‐33 signaling and are negatively associated with asthma exacerbations, the relationship between sST2 and asthma severity is unclear." (PMID 40022441, 2025). "This suggests that IL-33 is an important mediator implicated in mast cell-epithelium crosstalk in asthma." (PMID 39707175, 2024). "Further research focusing on the association between TSLP and IL-33 gene polymorphisms and asthma is expected to significantly advance disease management." (PMID 38731070, 2024). "Genetic studies have shown significant associations between IL1RL1 and IL33 genetic variants and allergic diseases such as asthma, atopic dermatitis and EoE in humans." (PMID 39654685, 2024). "This biologic targets IL-33, thereby potentially mitigating the inflammatory cascade associated with asthma and other allergic conditions." (PMID 39457624, 2024). "Asthma was associated with the increased expression of pro-inflammatory cytokines, including IL-2, IL-5, IL-13, IL-17A, IL-22, IL-33, and TNF-α, and reduced levels of anti-inflammatory cytokine, IL-10 and adipokine, leptin in the circulation." (PMID 39902293, 2024). "The interleukin‐33/interleukin‐1 receptor‐like‐1 (IL‐33/IL1RL1) signalling pathway is implicated in asthma pathogenesis, with IL1RL1 nonsynonymous genetic polymorphisms associated with disease risk." (PMID 39301832, 2024). "Most gene-disease pairs displayed deleterious associations, except IL33-asthma (0.99, P = 8.09 × 10−16) and IFIH1-psoriasis (0.98, P = 1.02 × 10−6)." (PMID 39009607, 2024). "Considering the allele model, for both tested SNPs of IL-33, we observed that patients with asthma, atopic asthma, and atopy statistically less frequently possess the risk allele." (PMID 38731070, 2024). "The magnitude of IL‐33 signalling is determined by asthma‐associated structural variation in IL33 receptor." (PMID 39301832, 2024). "IL-33 is mainly associated with type 2 immune responses and has been implicated in the development of asthma." (PMID 38714349, 2024). "Blockade of IL-33 has been shown to inhibit the Th2-type inflammatory pathway, which is the most common pathogenic pathway of asthma." (PMID 39598682, 2024). "In another study, the authors focused on the association of the SNP with IL-33 expression in tissues related to asthma." (PMID 38731070, 2024). "IL-33 plays a key role in type 2 inflammation, especially in respiratory diseases, where it is implicated in common respiratory diseases such as asthma, allergic rhinitis, chronic obstructive pulmonary disease and acute respiratory distress syndrome." (PMID 39301028, 2024).
asthma (continued). "While numerous studies have confirmed the association of IL-33 with respiratory diseases such as asthma, allergic rhinitis, COPD, and pulmonary fibrosis limited research has investigated the role of IL-33 in other respiratory conditions like ARDS." (PMID 39301028, 2024). "Together with the IL33 locus, one of the most highly reproduced association signals in genome‐wide association studies of asthma, spans the IL1RL1 gene." (PMID 39301832, 2024). "This review highlights the complex interplay of epithelial-derived alarmins, particularly TSLP, IL-33, and IL-25, in orchestrating the skewed T2 inflammatory phenotype that underlies the pathology in asthma." (PMID 39457624, 2024). "IL-33-mediated mast cell activation has also been shown to be associated with a neutrophilic phenotype of severe asthma." (PMID 39194521, 2024). "While the PWAS discovery of IL33 was entirely based on variants within the coding region, it was shown that a 5 kb region in the vicinity of the IL33 locus is implicated in asthma." (PMID 39406500, 2024). "IL-33 is known to induce a type 2 inflammatory response, which is implicated in allergic inflammation observed in conditions like asthma and atopic dermatitis." (PMID 39301028, 2024). "SNPs spanning the IL-33 region mediate the development of asthma among individuals carrying this risk allele." (PMID 38731070, 2024). "Mounting evidence has revealed that IL-33 levels are elevated within the serum or tissue under inflammation-associated diseased conditions, such as heart failure, atherosclerosis, asthma, sepsis, trauma and pulmonary fibrosis." (PMID 39713054, 2024). "IL-33 rs992969 SNP, as well as IL-33 rs1888909 SNP, showed a significant association with asthma, atopic asthma and atopy in the allele model." (PMID 38731070, 2024). "For instance, IL-33 has been associated with asthma susceptibility and can contribute to both T2 and non-T2 inflammation." (PMID 39194521, 2024). "Twenty-four pathways in WT_IL-25/IL-33 transcriptomes were associated with cytokine–cytokine receptor interaction, asthma, arginine metabolism, proline, cysteine, methionine, glycine, serine, threonine, glutamine, and glutamate." (PMID 37337050, 2023). "Polymerase 1 and transcript release factor (PTRF, encoding by Cavin-1) regulates interleukin 33 (IL-33) release, which is implicated in asthma development." (PMID 37454215, 2023). "Some studies explored the association between IL‐33 in peripheral blood and some other biomarkers (including total IgE and sputum eosinophils) in asthma." (PMID 37102668, 2023). "First, this study focuses on the acute model of type 2 inflammation to address the role of Tollip deficiency-mediated excessive ATP and IL-33 release in acute exacerbations of type 2-high asthma." (PMID 38124753, 2023). "The fungal allergen (Alternaria alternate) is a rapid IL-33 inducer in the airways and is associated with asthma severity and exacerbations." (PMID 37607012, 2023). "Authors here show that IL-33, a cytokine that is produced by the inflammatory microenvironment, promotes type-2 cytotoxic T cell development, which is linked to asthma exacerbations." (PMID 37612281, 2023). "An IL‐33 loss‐of‐function mutation protects children from asthma and has been associated with a lower blood eosinophil count." (PMID 35986608, 2023). "Of interest, in children, severe asthma is more common in the case of sensitization to the fungus Alternaria alternata (Alt) and is strongly associated with increased IL-33 sputum levels." (PMID 37153601, 2023). "The expression of IL-33 in bronchial epithelial cells and respiratory smooth muscle cells is associated with airway hyperresponsiveness in asthma patients." (PMID 38082335, 2023). "IL-33 is a novel member of the IL-1 family of cytokines and has been implicated in the modulation of inflammatory disorders such as asthma, atopic dermatitis, and some cancers 11-17." (PMID 37056569, 2023).
asthma (continued). "IL-33 has been implicated in allergy, asthma and parasitic diseases, but also increasingly in chronic inflammatory conditions such as arthritis." (PMID 36595532, 2023). "Numerous asthma susceptibility genes, for instance, IL33, IL1RL1, MUC5AC, TSLP, CDHR3, and KIF3A, are expressed in the airway epithelium." (PMID 36832296, 2023). "Genome‐wide association study (GWAS) indicated that the gene polymorphisms of IL‐33/IL‐1R1 pathway showed association with development of wheeze and asthma in early childhood." (PMID 37102668, 2023). "A negative correlation with severity indicators, such as the AQLQ questionnaire and spirometry (FVC and FEV1), was seen for all signatures indicating that a higher IL‐33‐activated ES is associated with poorer asthma control and quality of life." (PMID 35986608, 2023). "Another gene-related research presented that IL-33 is related to asthma and that both IL-33 and IL1RL1 are linked to disease susceptibility." (PMID 37153553, 2023). "IL33 is an asthma susceptibility gene and IL-33 is released from the bronchial epithelium during HRV infection in asthmatic subjects." (PMID 36366528, 2022). "Many genes, including Il33, Cxcl5, Cxcl15, Ccl20, Cxcl3, Cxcl1, C3, and Pfn1, which have been linked to asthma pathogenesis, showed a cell type-specific response to HDM." (PMID 35627266, 2022). "The epithelial cytokine IL-33 which is released by airway epithelial cells in response to stimulants, such as allergens, is implicated in asthma susceptibility and severity." (PMID 35743783, 2022). "A rare variant in IL33 correlates with low eosinophil counts and reduced risk of asthma in Europeans." (PMID 36311787, 2022). "Several of these DEGs associated with Tet1 loss in AT2 cells (Il33, Areg and Bpifa1, Hspa8 and Lgals3 (also DEGs in ciliated cells)), have been previously linked to asthma." (PMID 35627266, 2022). "The asthma susceptibility gene, IL-33, encodes an epithelial-derived cytokine released following HRV infection but its impact on MC antiviral responses has yet to be determined." (PMID 36366528, 2022). "Many of the SNPs in the IL-33 gene that have been studied in asthmatic patients have demonstrated a positive and direct association with asthma." (PMID 35406669, 2022). "Genome-wide association studies in patients with asthma showed that IL33 and IL1RL1 (ST2) were the genes most associated with asthma." (PMID 35025767, 2022). "Bronchoalveolar lavage (BAL) levels of IL-33 inversely correlated with lung function in patients with asthma, and IL33 mRNA expression was associated with more severe disease." (PMID 35025767, 2022). "Despite their overlapping function in asthma and inflammatory diseases associated with type 2 immunity, existing studies suggest that IL-25 and IL-33 elicit largely distinct immune pathways in CRC." (PMID 36263033, 2022). "In lung biopsies of asthmatic patients, IL-33 expression is increased and IL-33 polymorphisms can increase asthma susceptibility." (PMID 34531552, 2022). "Higher expression of IL-33 is associated with asthma severity, and IL-33 is considered a promising therapeutic target for eosinophilic asthma." (PMID 35720347, 2022). "CGRP also exhibits duality, suppressing IL-33 + NMU-ILC2 activation but restoring asthma-like phenotypes in OVA-challenged PNEC-deficient mice given GABA." (PMID 36704754, 2022). "One of the nasal-specific TWAS genes, interleukin-33 (IL33), for which increased expression was associated with increased asthma risk, was the most strongly associated AOA TWAS gene and the second most strongly associated TWAS gene for COA." (PMID 35347136, 2022). "Although the immunologic functions of IL-25 and IL-33 appear to overlap almost entirely, one large-scale genome-wide association study (GWAS) of asthma has indicated a more pronounced role for IL-33 in asthmatic patients." (PMID 35546400, 2022). "The best evidence for the IL-33/ST2 axis playing a pathogenic role in asthma comes from the results of randomized clinical trials." (PMID 35406669, 2022).